FAN1 (FANCD2 and FANCI associated nuclease 1)
Diseases named in the same sentence as FAN1 in open-access papers (continued):
Sharing a sentence is not in itself a finding about the gene and the disease.
anaplastic astrocytoma (1 paper, 2021). "In detail, one patient collected tumor specimens in all stages of MT in the present cohort.PRKCQ,PPIF,NRP1,MEFV,GGT1,FAN1, andBTKmutations were found in both DA and anaplastic astrocytoma, whereas mutations ofTBC1D19,ESRRA,DIAPH2,COG6, andCBWD3occurred in HGA." (PMID 34430964, 2021).
atherosclerosis (1 paper, 2022). A disease characterized by the build-up of fatty material and calcium deposition in the arterial wall resulting in partial or complete occlusion of the arterial lumen. "Taken together, genotyping the FAN1-[TG]N TR may have the potential to increase the diagnostic accuracy of atherosclerosis given carotid IMT data and, more broadly, may inform effects of trans-acting TR-containing genes expressed during development and/or adulthood." (PMID 36509785, 2022).
autoimmune disease (1 paper, 2022). A disorder resulting from loss of function or tissue destruction of an organ or multiple organs, arising from humoral or cellular immune responses of the individual to their own tissue constituents. "FAN1 has not yet been associated with autoimmune diseases or IRAE." (PMID 35053465, 2022).
Fanconi Syndrome (1 paper, 2024). "FAN1 inactivation may cause Fanconi syndrome in Basenjis by sensitization of kidney proximal tubule cells to toxin-mediated DNA crosslinking, resulting in the accumulation of genomic and mitochondrial DNA damage in the kidney." (PMID 39596669, 2024).
kidney injury (1 paper, 2023). Trauma to the kidney. "Furthermore, patients with biallelic FAN1 pathogenic variants may also be at increased risk of cancer and acute kidney injury from treatment with cisplatin or other environmental toxins." (PMID 37107275, 2023).
liver disease (1 paper, 2024). "The clinical presentation of FAN1-related disease was multifaceted, and not yet described manifestations were observed besides kidney and liver disease." (PMID 38892095, 2024).
lung disease (1 paper, 2025). "The remaining 11 genes in the region encode proteins associated with neurologic disorders (APBA2, CHRFAM7A, MTMR10, FAN1), skin and eye pigmentation or development (OCA2, HERC2, TJP1, TRPM1), nephritis (ARHGAP11B, MTMR10, FAN1), and lung disease (ENTREP2, NSMCE3)." (PMID 40013929, 2025).
lung fibrosis (1 paper, 2024). "However, the autopsy report did not describe the honeycomb lung and marked signs of chronic cor pulmonale; hence, the severity of lung fibrosis which was attributed to the FAN1 mutation in retrospect could not have been advanced." (PMID 38892095, 2024).
mucositis (1 paper, 2024). Mucositis is inflammation and damage of the mucous membranes lining the mouth and other parts of the gastrointestinal (GI) tract. "We and other groups have previously reported the tissue protective effects of JP4-039 in various preclinical disease models, including FAN1 kidney disease, total body irradiation, radiation-induced mucositis and sulfite-induced striatal cell death." (PMID 39765862, 2024).
Nephropathy (1 paper, 2021). A nonspecific term referring to disease or damage of the kidneys. "The heterogeneity of the glomerular filtration rate slope despite a common genotype supports the role of modifying genetic factors or environment and genotoxins in FAN1-related nephropathy." (PMID 34386670, 2021).
osteosarcoma (1 paper, 2022). A usually aggressive malignant bone-forming mesenchymal neoplasm, predominantly affecting adolescents and young adults. "In contrast, published data from a FAN1−/− osteosarcoma cell line transduced with a 118 CAG repeat showed that overexpression of wild-type, D960A or R507H FAN1 was equally effective at slowing repeat expansion." (PMID 35379994, 2022).
ovarian carcinoma (1 paper, 2025). A malignant neoplasm originating from the surface ovarian epithelium. "Although variants in the FAN1 gene have been identified in 14 BC and ovarian cancer patients in families with early-onset cancers, the association of these variants with increased BC risk has not been consistent." (PMID 40941673, 2025).
pancreatic cancer (1 paper, 2020). "We found a patient carrying the FAN1 c.149T>G (p.Met50Arg) variant which was previously associated to functional defects and pancreatic cancer predisposition." (PMID 32635641, 2020). "Recent reports implicate FAN1 as a CRC and pancreatic cancer predisposing gene." (PMID 32635641, 2020).
placental disease (1 paper, 2023). "This is novel as FAN1 protein correlation with placental disease has not been previously shown and merits more investigation." (PMID 37190039, 2023).
R6/ (1 paper, 2021). "Finally, to demonstrate the significance of this interaction in vivo, we showed that FAN1 and MLH1 interact in cortical extracts of zQ175 and R6/2 HD mice." (PMID 34469738, 2021).
upper respiratory tract infections (1 paper, 2024). "The clinical phenotype of FAN1-mutation related disorder also includes recurrent upper respiratory tract infections and an increased risk of malignancy." (PMID 38892095, 2024).
cancer (13 papers, 2016 to 2025). A tumor composed of atypical neoplastic, often pleomorphic cells that invade other tissues. "Bi-allelic pathogenic variants in the FAN1 gene lead to a multisystem disorder that includes chronic kidney disease, pulmonary infections and fibrosis, and increased susceptibility to cancer." (PMID 37107275, 2023). "FAN1 patients may be more susceptible to developing cancer at extrarenal sites and sepsis after kidney transplantation." (PMID 37107275, 2023). "The synthetic toxicity observed in the FAN1/BRCA2 double knock-down cells and the aggravated genomic instability of BRCA2-depleted cells expressing the FAN1 PIP*, UBZ* or ND mutants suggests that inhibition of FAN1 function in BRCA-deficient cancers may cause cell lethality." (PMID 29051491, 2017). "Thirteen of them were variants predicted as pathogenic by in silico tools, identified in well-known CRC predisposing genes such as APC and MUTYH, as well as variants in newly emerging cancer predisposing genes such as MSH3 and FAN1." (PMID 32635641, 2020). "Further, rare mutations in MSH3 and FAN1 are known to cause rare forms of cancer, although they do not primarily affect the central nervous system." (PMID 39801710, 2025). "The genes FAN1, MSH6, and FANCI were among those with the highest number of VUS, complicating clinical decision-making due to the uncertain impact of these variants on hereditary cancer risk." (PMID 39710803, 2024). "Although the loss of FAN1 function does not increase the burden of cancer, some mutations have been found in tumours, including mutations abolishing nuclease/exonuclease activity." (PMID 35883600, 2022). "Based on our findings, it appears highly probable that, as in the case of EXO1, mutations in the FAN1 gene will also not segregate with cancer." (PMID 34228493, 2021). "Based on the canSAR cancer drug discovery platform and using the chemical properties and bioactivity of small molecules annotated in ChEMBL database, it has been estimated that FAN1 is among 107 DNA damage response (DDR) factors predicted to be druggable." (PMID 33240760, 2020). "Additionally, FAN1 functional status in cancer cells might be used as a biomarker to predict response to treatment." (PMID 35883600, 2022). "However, the role of FAN1 in cancer predisposition is currently a matter of controversy since no significant increase in the burden of FAN1 mutations are detected in CRC cases versus controls." (PMID 32635641, 2020). "Therefore, inhibition of FAN1 could be used to sensitize cancer cells to conventional chemotherapy." (PMID 35883600, 2022).
tumor (6 papers, 2019 to 2025). "Increased FAN1 expression in tumours refractory to treatment has been observed in breast and ovarian cancers." (PMID 35883600, 2022). "Of the promoters gaining methylation in our sample, many have already been shown to have tumour suppressor activity, including RORa, FAN1, PRDM1, CYGB, L3MBTL4, EPB41L3, with ZNF471 and ZNF671 being specifically silenced by methylation." (PMID 31357948, 2019). "Nine cases with germline variants in HR-related genes PALB2, BRCA1, RAD51C, FAN1 and CHEK2 also showed evidence of enrichment of the germline variant in the tumor, while the other 12 cases with HR-related gene variants (seven FAN1, three CHEK2, one BRIP1, one NBN) did not." (PMID 33917078, 2021).
Kidney Disease (4 papers, 2021 to 2024). "In this regard, using KIN as a model for FAN1-deficient kidney disease can be a valuable platform for investigating the mechanisms by which CKD develops due to defective DNA repair." (PMID 37759541, 2023). "Our study suggests that the hiPSC-derived kidney organoid system can effectively recapitulate the phenotype of FAN1-deficient kidney disease." (PMID 37759541, 2023). "Previous studies have successfully modeled FAN1-deficient kidney disease using zebra fish and mice, demonstrating increased DNA damage response (DDR), apoptosis, and karyomegaly." (PMID 37759541, 2023). "The aim of this study was to explore the possibility of using a human induced pluripotent stem cell (hiPSC)-derived kidney organoid system for modeling FAN1-deficient kidney disease, also known as KIN." (PMID 37759541, 2023). "However, no studies have yet reported on the modeling of FAN1-deficient kidney disease using an hiPSC-derived kidney organoid system." (PMID 37759541, 2023).
psychiatric disorder (2 papers, 2020 to 2021). A disorder characterized by behavioral and/or psychological abnormalities, often accompanied by physical symptoms. "On the other hand, a study of the FAN1 gene suggests that this could be a driver gene in the 15q13.3 locus for psychiatric disorders since this gene encodes DNA repair enzyme, thus abnormalities in DNA repair could lead to susceptibility to SCZ or ASD." (PMID 33510659, 2020). "The 15q13.3 microdeletion syndrome is a genetic disorder characterized by a wide spectrum of psychiatric disorders that is caused by the deletion of a region containing 7 genes on chromosome 15 (MTMR10, FAN1, TRPM1, MIR211, KLF13, OTUD7A, and CHRNA7)." (PMID 33785025, 2021).
kidney (1 paper, 2024). "In the Fan1 knockout mouse model, Fan1-deficient kidney proximal tubular cells accumulated the DNA damage after genotoxic or obstructive kidney injury and displayed dedifferentiation and tubular injury." (PMID 38892095, 2024).
FAN1 also shares sentences with these, for which no sentence is quoted: autism spectrum disorder (2 papers); epilepsy (2); hereditary cancer (2); Intellectual disability (2); neurologic disorders (2); pancreatitis (2); amyloidosis (1); attention deficit-hyperactivity disorder (1); bipolar disorder (1); bladder cancer (1); Brain atrophy (1); breast carcinoma (1); breast tumor (1); cognitive decline (1); colitis (1); communication disorder (1); dyslexia (1); familial colorectal cancer type X (1); focal segmental glomerulosclerosis (1); genetic disorder (1); Hepatitis B (1); hereditary colorectal cancer (1); microdeletion syndrome (1); nephritis (1); neurodegenerative disease (1); schizoaffective disorder (1).